STXBP5 (syntaxin binding protein 5)
Description:
Plays a regulatory role in calcium-dependent exocytosis and neurotransmitter release. Inhibits membrane fusion between transport vesicles and the plasma membrane. May modulate the assembly of trans-SNARE complexes between transport vesicles and the plasma membrane. Inhibits translocation of GLUT4 from intracellular vesicles to the plasma membrane.
Synonyms: LLGL3; tomosyn; tomosyn-1; LGL3; Nbla04300
Tractability: Antibody: UniProt places it where antibodies can reach, with medium confidence; its Gene Ontology location is reachable by antibodies, with medium confidence. PROTAC: its protein half-life has been measured.
Gene: Protein-coding gene on chromosome 6 (147,203,710 to 147,391,010, forward strand). Ensembl gene ENSG00000164506.
Subcellular location: Cytoplasm; Cell membrane; Cytoplasmic vesicle membrane; Cytoplasmic vesicle, secretory vesicle, synaptic vesicle; Synapse
Subcellular location (Human Protein Atlas): Cytosol
Gene Ontology:
Molecular function: GTPase activator activity; myosin II binding; syntaxin binding; syntaxin-1 binding
Biological process: exocytosis; Golgi to plasma membrane transport; positive regulation of exocytosis; regulation of exocytosis
Cellular component: cytosol; acetylcholine-gated channel complex; cytoplasm; plasma membrane; cytoplasmic vesicle membrane; synapse; synaptic vesicle
Genetic constraint (gnomAD): Loss-of-function variants: 32 observed, 124.95 expected, observed/expected ratio (o/e) 0.26, 90% interval 0.19 to 0.34. The upper end of that interval is the gene's LOEUF score, 0.34, which puts it in group 1 of 6, group 1 being the genes least tolerant of losing a copy. Missense variants: 1,080 observed, 1,341.5 expected, observed/expected ratio (o/e) 0.81, 90% interval 0.76 to 0.85. Synonymous variants: 471 observed, 482.67 expected, observed/expected ratio (o/e) 0.98, 90% interval 0.9 to 1.05.
Homologues: Orthologues: chimpanzee STXBP5 (100% identical), macaque STXBP5 (99% identical), rabbit STXBP5 (98% identical), pig STXBP5 (98% identical), mouse Stxbp5 (97% identical), rat Stxbp5 (97% identical), dog STXBP5 (91% identical), guinea pig STXBP5 (89% identical), tropical clawed frog stxbp5 (89% identical), zebrafish stxbp5a (79% identical), zebrafish stxbp5b (75% identical), Drosophila melanogaster Tomosyn (46% identical), and 1 more. Paralogues in human: STXBP5L (67% identical), LLGL2 (26% identical), LLGL1 (26% identical).
Diseases named in the same sentence as STXBP5 in open-access papers:
STXBP5 is named in the same sentence as 19 diseases in open-access papers, as found by Europe PMC text mining. Sharing a sentence is not in itself a finding about the gene and the disease. The quoted sentences say what the papers report.
autism (3 papers, 2013 to 2024). Persistent deficits in social interaction and communication and interaction as well as a markedly restricted repertoire of activity and interest as well as repetitive patterns of behavior. "Similarly, other autism candidate genes including NLGNs, IQSEC2, DOCK4, and STXBP5, are also implicated in AMPAR trafficking." (PMID 38316900, 2024). "Additional alterations were found in previously reported autism candidate genes, including three genes with alterations in multiple families (CEP290, CSMD1, FAT1, and STXBP5)." (PMID 24410847, 2014).
venous thromboembolism (3 papers, 2021 to 2025). Occlusion of the lumen of a vein by a thrombus that has migrated from a distal site via the blood stream. "STXBP5 is expressed in human endothelial cells and is associated with venous thromboembolism that manifests with blood clots, and leads to secondary changes in the blood vessels and alterations to the blood flow." (PMID 36979743, 2023). "On the one hand, a study showed that gene STXBP5 inhibits endothelial exocytosis and promotes platelet secretion, and the variation within STXBP5 is a genetic risk for venous thromboembolic disease." (PMID 33536081, 2021). "Furthermore, syntaxin binding protein 5 (STXBP5), identified as a potential target of hsa-miR-12136, has been linked to venous thromboembolism, a condition characterized by the formation of blood clots, secondary vascular changes, and altered hemodynamics." (PMID 40230453, 2025).
breast carcinoma (1 paper, 2021). "Higher expression of STXBP5, GALP, and LOC387646 indicated an unfavorable prognosis for breast cancer (BC) patients." (PMID 34947885, 2021).
dengue (1 paper, 2025). "Syntaxin-binding protein 5 (STXBP5), expressed in endothelial cells and platelets, has emerged as a candidate; its deficiency elevates P-selectin and von Willebrand factor (vWF), promoting pathological platelet adherence, a hallmark of severe dengue." (PMID 41583452, 2025). "The identified DEPs, such as STXBP5, THBS1, and PRG2, have potential as biomarkers for predicting severe dengue outcomes." (PMID 41583452, 2025). "STXBP5 knockout in mice reduces platelet factor 4 (PF4/CXCL4) secretion, mirroring the observed PF4 reduction, which correlates with dengue severity." (PMID 41583452, 2025). "Despite the small sample size (n = 18) limiting generalizability, this approach enabled deep profiling in a resource-limited setting and revealed candidate biomarkers (e.g., thrombospondin-1 and STXBP5) and pathways (e.g., complement and TGF-β) for severe dengue." (PMID 41583452, 2025).
endothelial dysfunction (1 paper, 2024). In vascular diseases, endothelial dysfunction is a systemic pathological state of the endothelium (the inner lining of blood vessels) and can be broadly defined as an imbalance between vasodilating and vasoconstricting substances produced by (or acting on) the endothelium. "Higher intensity of vWF and lower STXBP5, as demonstrated in the CSPH group in our study, supports the role of endothelial dysfunction as an important factor in PH development." (PMID 38603681, 2024).
epilepsy (1 paper, 2017). A brain disorder characterized by episodes of abnormally increased neuronal discharge resulting in transient episodes of sensory or motor neurological dysfunction, or psychic dysfunction. "Given its role in neurotransmitter release, STXBP5/tomosyn‐1 is an ideal target to manipulate presynaptic glutamatergic neurotransmission to understand how glutamatergic neurotransmission contributes to kindling‐induced epilepsy." (PMID 28948088, 2017).
schizophrenia (1 paper, 2023). A major psychotic disorder characterized by abnormalities in the perception or expression of reality. "Based on existing research, the host gene of hsa_circ_0005035 (i.e., IGF1R) has been observed to play an important role in the pathogenesis of schizophrenia, and STXBP5 (i.e., the host gene of hsa_circ_0007762) were involved in the docking and fusion of synaptic vesicles and presynaptic membranes." (PMID 37816766, 2023).
Stroke (1 paper, 2025). Sudden impairment of blood flow to a part of the brain due to occlusion or rupture of an artery to the brain. "In a proteomics stroke study, researchers identified ICAM-2, STXBP5, PLGLA, C3, and IGHV3-64 as candidate biomarkers in blood, yielding a high (75% to 88%) sensitivity for identifying stroke patients." (PMID 40362186, 2025).
thromboembolic disease (1 paper, 2021). "The identified risk factors on chromosomes 2, 6, 7, 8, 10, 16, and 17 contain genetic variants and genes related to cilia dysfunctions (DNAH7 and CLUAP1), cardiovascular diseases (DES and SPEG), thromboembolic disease (STXBP5), mitochondrial dysfunctions (TOMM7), and innate immune system (WSB1)." (PMID 33536081, 2021).
tumor (3 papers, 2020 to 2024). "Since the protein is present in normal breast tissue, STXBP5 mRNA dysregulation could affect syntaxin binding protein 5 (STXBP5) protein levels in BRCA tumor tissue." (PMID 32241256, 2020).
cancer (2 papers, 2020 to 2023). A tumor composed of atypical neoplastic, often pleomorphic cells that invade other tissues. "As a result, seven genes (FGF10, SERINE2, LSAMP, STXBP5, PDE5A, GLI2, FRMD6) were screened to develop the cancer associated fibroblasts (CAFs)-related risk signature (CAFRS)." (PMID 37280069, 2023).
STXBP5 also shares sentences with these, for which no sentence is quoted: type 1 von Willebrand disease (2 papers); amyotrophic lateral sclerosis (1); Arterial thrombosis (1); breast tumor (1); cardiovascular diseases (1); diabetes (1); Obesity (1); von Willebrand Disease (1).